IRS1 (insulin receptor substrate 1)
Diseases named in the same sentence as IRS1 in open-access papers (continued):
Sharing a sentence is not in itself a finding about the gene and the disease.
breast cancer (continued). "Breast cancer cells can develop metformin resistance by triggering IGF-1R target insulin receptor substrate-1 (IRS-1)/ERK signaling through overactivation of FGFR1; IRS-1 acts as a critical crosstalk mediator between IGF-1R and FGFR1 pathways, encompassing a feedback loop between IRS-1 and MAPK/ERK." (PMID 36017326, 2022). "The expression of IRS1 in breast cancer cells varies with tumor invasiveness." (PMID 35387129, 2022). "We discovered three genes: PRC1, GGTLC1, and IRS1 that may mediate breast cancer chemotherapy resistance through immune pathways and found that immune regulation disorders may be some of the key factors in the survival of breast cancer patients." (PMID 35387129, 2022). "IRS-1 was the major known isoform and reported to promote tumor growth in breast cancer." (PMID 37435453, 2022). "Thus IRS-1 inhibition represents a novel strategy to target phospho-PR-specific signalling in ER+ breast cancer, particularly in the endocrine-resistant setting." (PMID 33144693, 2021). "Moreover, we detect significantly increased IGF2 in blood and IRS1 in the tumors of breast cancer patients with poor response to Herceptin-containing regimens." (PMID 33976188, 2021). "Given our data linking phospho-PR-B and IRS-1, we next investigated whether pharmacologically targeting the IR/IRS-1 pathway abrogates CSC outgrowth in PR+ breast cancer models." (PMID 33144693, 2021). "Additionally, in breast cancer cells, cell cycle arrest mediated by IGF1 was linked with reduced phosphorylation of tyrosine residues in insulin receptor substrate 1 (IRS1)." (PMID 34948455, 2021). "Related to these findings, Yang and co-workers reported that the tyrphostin NT157 downregulates IRS1/2 proteins in breast cancer cell lines by binding to the IGF1R, increasing serine phosphorylation of IRS1/2, leading to their degradation and reduced IGF1R signaling." (PMID 32226608, 2020). "Furthermore, miR-148a-3p can depress cell proliferation by dampening functional expression of IGF1R and IRS1, whose signaling is crucial in luminal breast cancer subtype." (PMID 32085669, 2020). "Similar to our results, a study has found out that miR-195 inhabited tumor growth and angiogenesis by regulating IRS1 in breast cancer, suggesting that miR-195 might be considered as be a potential therapeutic target in the treatment of breast cancer." (PMID 31210063, 2019). "Notably, high expression of IRS1 in breast cancer cells was positively correlated with aberrant phosphorylation of AKT, which was significantly associated with lymph node metastasis." (PMID 30594912, 2018). "MiR-152 inhibits tumor angiogenesis via targeting IGF-IR and IRS1 in breast cancer." (PMID 29743122, 2018). "mTORC1 inhibitors generally have a cytostatic effect on ER+ breast cancer cells, which is thought to be due in part to a loss of negative feedback signaling to activators upstream of PI3K including RTKs and IRS-1, driving activation of PI3K/AKT to promote cell survival." (PMID 29507656, 2018). "Ongoing investigation in our laboratory has motivated us to hypothesize that the molecular composition of plasma membrane microdomains associated with IGF-1R network receptors might dictate the tumorigenic activity of IRS-1/2 in breast cancer." (PMID 29152592, 2017). "Furthermore, our present work provides novel evidences which demonstrating that miR-30e inhibits tumor growth and chemoresistance via targeting IRS1 in breast cancer." (PMID 29162879, 2017). "In addition to PI3K, IRS-1/2 has become another potential target against the IGF-1R network in breast cancer." (PMID 29152592, 2017). "The miR-30e/IRS1 link may play a role in breast cancer as markers of metastasis and prognostic factors." (PMID 29162879, 2017). "Furthermore, cell growth rate in the presence of paclitaxel(4 nM) was assayed by CCK-8 proliferation assay at different time points; interestingly, forced expression of IRS1 reversed miR-30e-induced breast cancer cell chemosentivity to paclitaxel." (PMID 29162879, 2017).
breast cancer (continued). "miR-195 inhibited the tumor angiogenesis and growth by suppressing IRS1 in breast cancer." (PMID 28487599, 2017). "Similarly, the IGFBP3, IGF1R, IRS1, and PI3KCB genes have a purported relationship with breast cancer risk due to either their role in IGF1 signaling regulation, or association with strong breast cancer risk factors." (PMID 27376028, 2016). "Interestingly, our unpublished data demonstrate that adiponectin enhances phosphorylation and protein expression of IRS-1 in ERα-positive breast cancer cells, thus amplifying the IGF-I/IGF-IR growth signaling." (PMID 26236690, 2015). "In MCF-7 breast cancer cells, IRS-1 was detected at 400 and 1,300 kDa." (PMID 26074875, 2015). "The IRS-1 G972R polymorphism has earlier been correlated to risk of developing prostate 43, colon 44, and breast cancer 45, however, there are no published studies on NSCLC." (PMID 24500884, 2014). "Although direct targeting of IRS-1 may prove to be problematic, it may be achievable in ER+ breast cancer with the use of antihormones, as IRS-1 is an oestrogen-regulated gene." (PMID 21939528, 2011). "Furthermore, IRS-1 and IRS-2 have been implicated in the regulation of proliferation, survival and metastatic potential in a range of breast cancer cell lines." (PMID 21939528, 2011). "Other erbB receptors are also prevalent in breast cancer, and their interplay with IRS-1 remains unknown." (PMID 21939528, 2011). "Consequently, cotargeting IGF-IR and either erbB3 or IRS-1 should prove to be a more effective strategy for the treatment of ER+ breast cancer." (PMID 21939528, 2011). "In the present study, using a panel of ER+ breast cancer cell lines, we examined for the first time whether IRS-1 can contribute to erbB3 signalling in breast cancer and what impact this may have on IGF-IR signalling." (PMID 21939528, 2011). "In this study, we examined whether IRS-1 also associates with another erbB receptor family member, erbB3, and what impact this might have on IGF-IR signalling in three ER+ breast cancer cell lines." (PMID 21939528, 2011). "This inhibition of IRS-1 expression may contribute to the suppression of breast cancer by these antiestrogens." (PMID 19534786, 2009). "One important caveat to the IRS overexpression and knockout mouse mammary tumor studies is that the tumors that develop in both models are ER- and a possible preferential role for IRS-1 in ER+ tumor growth, which is suggested from the studies on human breast carcinoma cell lines, cannot be excluded." (PMID 19534786, 2009). "In multiple experimental systems including primary mammary tumors, cultured human cells, and Brca1-deficient mice, Shukla and colleagues showed that BRCA1 deficiency resulted in increased expression of IRS1, IGF1R and IGFBP2, and increased levels of serum IGF1." (PMID 19843326, 2009). "Suppression of IRS-1 expression by siRNA promotes apoptosis and renders ER+ breast carcinoma cells more sensitive to tamoxifen-stimulated cell death, whereas overexpression of IRS-1 confers resistance to TGF-β-induced cell death in hepatocellular carcinoma cells." (PMID 19534786, 2009). "Importantly, our results suggest that growth regulation of breast cancer by the IGF-IR is specifically dependent on IRS-1-mediated signalling." (PMID 17043687, 2006). "Co-targeting ERα via SERM or SERD treatment and IRS1 via NT-157 had an additive antiproliferative effect on cells expressing homozygous ERα Y537S, indicating a potential treatment avenue for restoring ET sensitivity to resistant breast cancers expressing ERα Y537S." (PMID 38036546, 2023). "Additionally, we found that specific knockdown of IRS1 expression or IRS1 gene deletion decreased the levels of p-Akt and p-FOXO3a in vivo, confirming that p-Akt/p-FOXO3a acted as downstream of IRS1 in Herceptin-resistant breast cancer cells." (PMID 33976188, 2021). "Moreover, ERα was shown to regulate the degradation of the IRS1 in breast cancer cells." (PMID 30692633, 2019).
breast cancer (continued). "In addition nuclear IRS-1 may be a useful marker to predict tamoxifen response in patients with early breast cancer, because a reduction in the nuclear localization of IRS-1 has a negative prognosis." (PMID 25114970, 2014). "In breast cancer, the role of miR-126 in tumor metastasis may be related to the negative regulation of insulin receptor substrate-1 expression and it inhibits endothelial cell recruitment and angiogenesis through the negative regulation of IGFBP2/IGF1/IGF1R and GAS6/ MERTK signaling pathways." (PMID 24350576, 2013). "Therefore IRS-1 and IRS-2 are most likely implicated in CRC and breast cancer (BC)." (PMID 23877285, 2013). "Interestingly, IRS-2 was identified as a positive regulator of metastasis in breast cancer, whereas IRS-1 may be a suppressor of metastasis." (PMID 23251408, 2012). "Consequently, targeting IRS-1 alongside such agents may prove to be a more effective strategy for the treatment of ER+ breast cancer, particularly when heregulins are abundant." (PMID 21939528, 2011). "Recently we reported that insulin receptor substrate 1 (IRS-1), classically an adaptor protein for the insulin-like growth factor type I receptor (IGF-IR), associates with the epidermal growth factor receptor in oestrogen receptor (ER)-positive (ER+) tamoxifen-resistant breast cancer cells." (PMID 21939528, 2011). "In the present study, we examined whether IRS-1 can associate with other erbB family members, notably erbB3, and whether this has a direct impact on IGF-IR signalling in three ER+ breast cancer cell lines (MCF-7, T47D and BT-474) previously shown to express IRS-1 protein." (PMID 21939528, 2011). "Interestingly, erbB3 also possesses the NPXY motifs recognized by IRS proteins and as such may bind IRS-1 in breast cancer cells." (PMID 21939528, 2011). "In MDA-MB-231 breast cancer cells, PEDF decreases the overall abundance of insulin receptor substrate 1 (IRS1), which is known to limit the downstream p-AKT pathway and, consequently, the cancer cell survival and proliferation." (PMID 40001923, 2025). "[Δ: Percentage of Dkk1-IRS reduction, IRS1: Dkk1-IRS in core needle biopsy tissue, IRS2: Dkk1-IRS in mammary carcinoma tissue]." (PMID 38254908, 2024). "FOXO3a accelerated the trastuzumab resistance of HER2-positive breast cancer through targeting and up-regulating IGF2/IGF-1R/IRS1 signaling." (PMID 37529418, 2023). "In breast cancer, CDK12 frequently displays co-amplification and cooperation with the ERBB2 and interaction with oncogenic pathways, such as IRS1-ErbB-PI3K signaling." (PMID 38049758, 2023). "IRS-1/2 activates downstream signaling proteins such as PI3K/AKT/mTOR and Ras/Raf/MAPK, and this role has been documented in all molecular subtypes of breast cancer." (PMID 35366286, 2022). "In estrogen receptor-positive breast cancer cells, TRAF4 binding to IRS-1 stimulates proliferation of breast cancer cell lines and attenuates sensitivity to chemotherapy." (PMID 35242717, 2022). "In breast cancer, IGF-1 regulates cell growth through stimulation of the insulin growth factor receptor (IGF-1R), which consequently phosphorylates either insulin receptor substrate-1 (IRS-1) or insulin receptor substrate-2 (IRS-2)." (PMID 35366286, 2022). "Despite their homology, IRS1 and IRS2, have distinct functions in regulating breast cancer progression." (PMID 35846378, 2022). "Using a small molecule inhibitor of IRS-1, NT157, we showed striking reduction of ER+ breast cancer tumoursphere formation and expression of stem-like markers (ALDH1, CD44/CD24)." (PMID 33144693, 2021). "To further confirm that the TRAF4-IRS-1 interaction exists in breast cancer cells, we immunoprecipitated endogenous TRAF4 from MCF-7 cells and demonstrated a strong interaction with IRS-1." (PMID 33991522, 2021). "IRS1 is constitutively activated in a variety of solid tumors, namely, CRC, breast cancers, leiomyomas, Wilms tumors, rhabdomyosarcomas, liposarcomas, leiomyosarcomas, and adrenal cortical carcinomas." (PMID 34900704, 2021).
breast cancer (continued). "Collectively, these data established an essential role for FOXO3a transcriptional regulation of specific miRNAs to control IGF2 and IRS1 expression, thereby altering Herceptin sensitivity in HER2-positive breast cancer cells." (PMID 33976188, 2021). "First, Herceptin-resistant breast cancer cells over-produced IGF2, triggering autocrine activation of the IGF-1R signaling, which required IRS1 expression." (PMID 33976188, 2021). "We interrogated the TCGA provisional dataset for association of gene expression alterations in the IGF signalling components analysed above (IGF-1R, IFG-2R, IGFBP4, IRS-1, IRS-2) with survival in breast cancer." (PMID 32792532, 2020). "Subsequently, the same authors explained the ATRA regulation of IRS-1 level by the ubiquitin-proteasome pathway, through PKCδ activation in the ATRA-sensitive breast cancer cell lines." (PMID 32012980, 2020). "In summary, breast cancer cells exhibits activation of multiple growth promoting factors: IGF-1R, IRS-1, PDZK1 and ER-α." (PMID 29787591, 2018). "Our results suggest that fulvestrant is an effective drug that inhibits the pathogenic/carcinogenic effects of estrogen dependent IGF-1R, IRS-1, ER-α and PDZK1 signaling pathways to control breast cancer progression." (PMID 29787591, 2018). "Fulvestrant should be used to inhibit multiple targets (IGF-1R, IRS-1, PDZK1 and ER-α) involved in breast cancer progression." (PMID 29787591, 2018). "The proteosomal degradation of IRS1 and IRS2 is blocked by interactions with the ERα in a breast cancer cell line." (PMID 29868002, 2018). "The potential tumor suppressors miR-148a and miR-152 are important for breast cancer cell proliferation, colony formation, and angiogenesis by targeting IGF-IR and IRS1 and inhibiting their downstream PI3K/AKT and MAPK/ERK signaling pathways." (PMID 28464803, 2017). "In breast cancer cells, miR-148a inhibits tumor angiogenesis via targeting IGF-IR and IRS1 and suppressing their downstream AKT and MAPK/ERK signaling pathways." (PMID 28464803, 2017). "IRS‐1 S612 phosphosite has also been described as competitive binding site between PI3K and SRC and is connected to transformation activity in mammary cancer cells expressing v‐SRC." (PMID 28675785, 2017). "To examine the biological significance of IRS-induced gene expression, we evaluated the induction of TGFβ mRNA by both IRS-1 and IRS-2 in breast cancer cells." (PMID 26991655, 2016). "IRS1, the first identified member of IRS family, is frequently overexpressed in many solid tumors such as hepatocellular, prostate, colorectal and mammary cancer." (PMID 26684358, 2016). "The Late IRS-1 gene signature showed the most significant enrichment in basal-like, HER2-enriched, and luminal B breast cancers (P = 1.03E-49)." (PMID 26991655, 2016). "Notwithstanding this presumption, a more recent study on breast cancer suggests that EGFR has the ability to recruit and phosphorylate IRS-1 at Y896." (PMID 25886138, 2015). "In breast cancer, miR-148a acts as a tumor suppressor via targeting IGF-IR (insulin-like growth factor-I receptor) and IRS1 (insulin receptor substrate 1) and further suppressing the downstream MAPK signaling pathway." (PMID 26692821, 2015). "Activation of PI3-kinase in the human breast cancer cell line MCF-7 by insulin-like growth factor-I results in cell cycle progression and tyrosine phosphorylation of IRS-1." (PMID 25114970, 2014). "In breast cancer, ER-regulated genes including FGFR1 and IRS1, and ERK1-regulating genes including IRF6 and TOM1L1, were aberrantly methylated." (PMID 24842468, 2014). "In the present study, we analyzed the coding region and short intron-exon borders of the insulin receptor substrate 1 and 2 (IRS-1 and IRS-2) genes in 12 cell lines derived from breast cancer (BC), 14 cell lines derived from CRC and 33 primary CRCs." (PMID 23877285, 2013).
breast cancer (continued). "We previously reported that PR SUMOylation is transcriptionally repressive at a limited number of endogenous gene loci, including HBEGF, IRS1, and STC1; all three gene products are known to contribute to breast cancer cell proliferation." (PMID 22697792, 2012). "In this study we report that α-TEA suppression of AKT via targeting IRS-1/PI3K leads to activation of proapoptotic Bad and caspase-9 in human breast cancer cells." (PMID 21119656, 2011). "Recently, we provided strong evidence that IRS-1 can function as a key signalling intermediate for EGFR, a receptor that drives the growth of a tamoxifen-resistant MCF-7 breast cancer cell line." (PMID 21939528, 2011). "Downregulation of IRS-1/PI3K pathways via JNK are critical for α-TEA and α-TEA+MEK or mTOR inhibitor-induced apoptosis in human MCF-7 and HCC-1954 breast cancer cells." (PMID 21119656, 2011). "IRS-1 can be recruited to IGF-IR and erbB3 in ER+ breast cancer cells, and this provides an adaptive resistance mechanism when these receptors are targeted individually." (PMID 21939528, 2011). "Western blot analysis demonstrated that both basal and HRGβ1-primed IRS-1 Y612 and Y896 phosphorylation levels were markedly reduced following incubation of MCF-7 and T47D breast cancer cells with siRNA-targeting erbB3 protein expression." (PMID 21939528, 2011). "These and previous findings identify IRS-1 as a key signalling component for both IGF-IR and erbB receptor tyrosine kinases in ER+ breast cancer cells and as an important convergence point for cross-talk between these two receptor tyrosine kinase families." (PMID 21939528, 2011). "In this study, we sought to determine if insulin receptor substrate-1 and -2 (IRS-1 and -2) mediate distinct biological effects in breast cancer cells." (PMID 17043687, 2006). "Insulin receptor substrate-1 and IRS-2 were expressed in T47D-YA breast cancer cells, which lack IRS-1 and -2 expression, yet retain functional IGF-IR." (PMID 17043687, 2006). "Though six IRS family members have been identified (IRS-1 to IRS-6), IRS-1 and -2 are the predominant signalling molecules utilised by the IGF-IR to mediate IGF-I action in breast cancer cells." (PMID 17043687, 2006). "In addition, hsa-miR-7-5p has been shown to act as a tumor suppressor in breast cancer, including TNBC, where it inhibits cell proliferation and migration by targeting oncogenes such as EGFR and IRS1." (PMID 40867247, 2025). "In breast cancer cells, ERα interacts with IRS1 and IRS2 independent of E2, thereby protecting against ubiquitination-induced degradation." (PMID 38649684, 2024). "The different functions of IRS1 and IRS2 in breast cancer are further evidenced by the fact that mouse mammary tumors lacking IRS2 have a significantly diminished ability to metastasize to the lungs, whereas tumors lacking IRS1 but expressing elevated IRS2 have enhanced metastatic potential." (PMID 36975518, 2023). "In fact, the results of research on the effect of IRS1 on drug resistance were not consistent, and most studies showed that the decline in IRS1 expression promoted the development of breast cancer drug resistance." (PMID 35387129, 2022). "Thus, our data indicated that IRS1 and IGF2 were functionally interdependent to control Herceptin sensitivity in HER2-positive breast cancer cells." (PMID 33976188, 2021). "Herein we hypothesise that molecular crosstalk between phospho-PR and IRS-1 mediates CSC behaviour and the emergence of endocrine resistance, properties of advanced breast cancer that are relevant to recurrent metastatic disease." (PMID 33144693, 2021). "We discover a negative feedback inhibition of IGF2/IGF-1R/IRS1 signaling in HER2-positive breast cancer cells to maintain basic cell survival and proliferation." (PMID 33976188, 2021).